ANGPTL4 (angiopoietin like 4)
Diseases named in the same sentence as ANGPTL4 in open-access papers (continued):
Sharing a sentence is not in itself a finding about the gene and the disease.
tumor (continued). "Notably, ANGPTL4 has been significantly associated with various cancers, and ACSL3, crucial for fatty acid metabolism, exhibits altered expression levels in cancer, signalling aggressive tumour behaviour and a poor prognosis." (PMID 37556076, 2023). "However, in the angiogenic-activated tumor endothelium, ANGPTL4 might reduce lipolysis potentially inhibiting lipase activity in a local manner." (PMID 38086791, 2023). "Thus, our study confirmed that ANGPTL4 might be involved in tumor progression and metastasis of CCA, resulting in poor prognosis." (PMID 35392474, 2022). "Finally, ANGPTL4 also appears to have a dual role in HCC, since its increased serum and hepatic levels are associated with an oncogenic activity, while at low expression/secretion levels ANGPTL4 acts as a tumour suppressor." (PMID 35409319, 2022). "However, there are few studies on the regulation of lipid metabolism by ANGPTL4 in tumour cells." (PMID 35285130, 2022). "Moreover, the hypoxic exosomal ANGPTL4 protein could be transported to bystander normoxic tumour cells, leading to radioresistance of the neighbours, while this effect was abolished when ANGPTL4 was knocked down in exosomes." (PMID 36050447, 2022). "Furthermore, immunohistochemical staining showed that Ki-67 levels in transplanted tumour tissue from the ANGPTL4-shRNA and ANGPTL4-shRNA + G groups were lower than those in the control + G group (both, p < 0.001), which suggests that ANGPTL4 promotes tumor proliferation in vivo." (PMID 36467503, 2022). "However, no more details were obtained, and it is still unclear whether it is the flANGPTL4, the truncated ANGPTL4 (nANGPTL4, cANGPTL4) or the cooperation of all three molecules that plays a role in tumor progression." (PMID 35461343, 2022). "To confirm whether the exogenous exosomal ANGPTL4 could increase the radioresistance of A549 xenograft tumours in mice, we injected different homologous exosomes into the tumour once daily for 3 days before irradiation followed by continually daily injection until mice sacrifice." (PMID 36050447, 2022). "Thus, ANGPTL4 expression disrupts vascular endothelial tight junctions, augments vessel permeability, and alters trans-endothelial barriers, ultimately facilitating tumor cell motility and the formation of metastases." (PMID 36074318, 2022). "Moreover, the primary source and the tumor microenvironment of ANGPTL4 may impact the biological functions." (PMID 35392474, 2022). "However, these previous studies merely focused on ANGPTL4 expression in tumor cells and it is unclear whether ANGPTL4 is highly expressed in CAFs, one of the most important mesenchymal cells in the TME, and how it relates to the prognosis of tumor patients." (PMID 34331381, 2021). "Interestingly, under hypoxic conditions, ANGPTL4 mRNA expression and protein level may be increased, which may promote tumor invasion, proliferation, growth, and metastasis." (PMID 34445141, 2021). "In addition, recent studies have shown that ANGPTL4 plays a key role in tumor metastasis." (PMID 34331381, 2021). "Thus, whether OA-enhanced metastasis in different tumor types is dependent on individual genes, such as ANGPTL4 and NOX4, or if tumor metastasis relies on reciprocal regulation of OA-responsive genes is an interesting pursuit." (PMID 32641980, 2020). "Third, the primary source and tumor microenvironment of ANGPTL4 may affect biological behaviors." (PMID 32928141, 2020). "Moreover, ANGPTL4 expression was significantly lower in HCC tissues than in non-tumor tissues." (PMID 29389861, 2018). "ANGPTL4 has been reported both as a pro- and an anti-angiogenic protein, regulating vascular integrity and angiogenesis in a context-dependent manner suggesting that it might be tumor-type dependent." (PMID 29389861, 2018). "Finally, a study only showed that ANGPTL4 may prevent tumor invasiveness and metastasis through modulation of both endothelial and tumor cell cytoskeleton organization." (PMID 28182091, 2017).
tumor (continued). "Similarly, ANGPTL4 may also promote the transition from subclinical micro-metastasis to symptomatic macro-metastasis by facilitating metastatic tumor growth." (PMID 26761211, 2016). "Importantly, recent studies support a role for ANGPTL4 as a regulator of tumor angiogenesis." (PMID 26761211, 2016). "Upregulation of several of these genes in TAMs is compatible with the pro-tumorigenic role of TAMs and may serve not only to skew TAM polarization but may also directly promote tumor progression, for instance via the secretion of soluble mediators, such as ANGPTL4." (PMID 25968567, 2015). "However, the role of PPARs in the regulation of ANGPTL-4 in tumour cells is controversial." (PMID 26508818, 2015). "Thus, we speculated that higher ANGPTL4 expression could represent an alternative tumor angiogenesis route which was resistant to VEGF inhibition, hence lead to a poor therapeutic effect of bevacizumab." (PMID 26620439, 2015). "Downregulation of ANGPTL4 mRNA in HCC was significantly associated with advanced tumor stage, presence of venous infiltration, poor differentiation, higher AFP level, appearance of tumor recurrence, and poor postoperative overall and disease-free survivals of HCC patients." (PMID 25148701, 2014). "Furthermore, the PPARβ/δ-ANGPTL4 pathway was shown to be involved in tumor cell invasion." (PMID 24721177, 2014). "Moreover, the non-tumor liver tissues remained normal after Ad-ANGPTL4 treatment." (PMID 25148701, 2014). "Downregulation of ANGPTL4 mRNA in HCC was significantly associated with advanced HCC stage, presence of venous infiltration, higher AFP level, poor differentiation, appearance of tumor recurrence, and poor postoperative overall and disease-free survivals of HCC patients." (PMID 25148701, 2014). "This ANGPTL4‐dependent proinflammatory SASP can promote human neutrophil activation in ex vivo assays, or tumor initiation in a KRAS‐dependent lung tumorigenesis model in mice." (PMID 41347893, 2026). "In the tumor microenvironment, tumor cells secrete factors such as VEGF, TGF-β1, and ANGPTL4 to downregulate claudin-5 and ZO-1, thereby weakening the endothelial barrier." (PMID 40574854, 2025). "We found that FGF15 and circulating tumor cells (CTCs) colocalized in CRCLM mouse models, while ANGPTL4 colocalized with CAFs." (PMID 39716892, 2025). "Our study is the first to report that ANGPTL4 encourages the polarization of tumor-infiltrating macrophages toward the M2 phenotype within the TME, highlighting the multifaceted role of ANGPTL4 in promoting tumor progression." (PMID 39910592, 2025). "Further, ANGPTL4 in KRASG12D-expressing pancreatic epithelial cells enhances ADM and PanIN formation, a tumor-promoting role of ANGPTL4 is suggested in a cell-autonomous manner." (PMID 39811640, 2025). "ANGPTL4 expression was positively correlated with an increased TGFB response in primary tumor cells (r = 0.23, p < 0.001) and metastatic tumor cells (r = 0.47, p < 0.001)." (PMID 40233044, 2025). "Angiopoietin-like protein 4 (ANGPTL4), a member of the ANGPTL family, is closely correlated with tumor growth, metastasis, and angiogenesis." (PMID 40520991, 2025). "To understand the effect of ANGPTL4 on tumor progression, we used CRISPR-Cas9 to generate KO of ANGPTL4 in CAKi-1 cells, a human ccRCC cell line that has WT VHL." (PMID 39105498, 2024). "Examination of the CCC TME revealed activation of several signalling pathways (HGF, ANGPTL4, HBEGF, and FGF) that promote tumour growth and angiogenesis." (PMID 39149248, 2024). "In conclusion, this study indicates that tumor-infiltrating ADSCs promote glycolysis and anoikis resistance in CRC cells and ultimately facilitate peritoneal metastasis via the TGF-β1/SMAD3/ANGPTL4 axis." (PMID 38643448, 2024). "Our findings underscore that ANGPTL4 promotes OC development via JAK signaling and induces angiogenesis in the tumor microenvironment through its interaction with ESM1." (PMID 38212795, 2024).
tumor (continued). "Expression of ANGPTL4, CD36 and FABP4, proteins involved in fatty acid metabolism, was analyzed in marginal tumor cells using an immune reactive score." (PMID 39456610, 2024). "Although these findings suggest that ANGPTL4 has an intrinsic role in inhibiting LAL to regulate lipid metabolism and suppress ccRCC tumor growth, there are still questions remaining, and several key directions and strategies can be considered." (PMID 39105498, 2024). "RAB11B-AS1, a long noncoding RNA (lncRNA), enhances VEGFA and angiopoietin-like 4 (ANGPTL4) expression in hypoxic BC cells in a HIF-2α-dependent manner, promoting tumor angiogenesis and metastasis." (PMID 38799423, 2024). "Another family member, angiopoietin-like 4 (ANGPTL4) blunts the polarization of macrophages toward the proinflammatory phenotype and decreases immune surveillance in tumor progression by downregulating CD8 T cell activation." (PMID 38012322, 2023). "This study established the differential expression of three key hypoxia genes, ANGPTL4, P4HA1, and VEGFA, which were correlated with several radiomic texture features, mainly focusing on tumour heterogeneity." (PMID 37048688, 2023). "Angiopoietin-like-4 (ANGPTL4) regulates lipids and BCAAs metabolism and is involved in tumor metastasis and progression." (PMID 37637065, 2023). "However, other studies suggest that the function of ANGPTL4 is highly tumor-type dependent, and the protein might act as an anti-angiogenic protein in some cancer types as its role may be altered depending on the proteolytic cleavage and posttranslational changes." (PMID 37688629, 2023). "ANGPTL4, LTB4R, CD72, and NUDT6 were downregulated, as their expression levels were higher in the healthy group and lower in the tumor group." (PMID 36911403, 2023). "The expression levels of ANGPTL4 and PPARD were notably higher in tumour tissue, whereas the expression levels of FABP1, SLC27A1 and OLR1 were elevated in normal tissue." (PMID 37556076, 2023). "This study shows that ANGPTL4 can promote the synthesis of fatty acids in NSCLC, so the effect of fatty acids in tumour cells on ANGPTL4 expression and its mechanism need to be further studied." (PMID 35285130, 2022). "ADRB2, ANGPTL4, BDNF, CBLC, CX3CR1, and IL3RA were found markedly different expression between the tumor and normal group." (PMID 35833114, 2022). "Further in vivo experiments confirmed the roles of exosomal ANGPTL4 in the induction of radioresistance and ferroptosis inhibition in NSCLC xenograft tumours." (PMID 36050447, 2022). "While these data are suggestive of an oncogenic role of ANGPTL4, other studies reported that both the levels of ANGPT4 mRNA and the copy number of the gene are lower in HCC samples than in non-tumor tissues of the same patients." (PMID 36074318, 2022). "HIF-1α promotes EMT in cancer cells by activating the transcription of genes in the LOX family, and induces angiopoietin-like-4 (ANGPTL4), resulting in tumor growth and resistance to anoikis." (PMID 35740397, 2022). "We found that ANGPTL1, ANGPTL3, ANGPTL4, ANGPTL6, and ANGPTL7 were differentially expressed between tumor and normal tissues." (PMID 35692877, 2022). "Up- or down- regulation of ANGPTL4 positively interrelated to the radioresistance of NSCLC cells and xenograft tumours." (PMID 36050447, 2022). "Mechanistically, it was shown that soluble ANGPTL4 secreted by metastatic TNBC cells disrupts the integrity of endothelial cell junctions in capillaries within the lungs and brain, thereby allowing tumor cells to access and seed in the respective parenchyma." (PMID 36074318, 2022). "To confirm that ANGPTL4 can regulate the occurrence of pyroptosis and apoptosis through the NLRP3\ASC\Caspase 8 pathway, we used tissue proteins from the xenograft tumor to re-verify the results." (PMID 36467503, 2022). "In this study, two genes (ANGPTL4 and PLK1) of the IGSPP that we constructed were involved in the regulation of the tumor cell cycle." (PMID 35581376, 2022).
tumor (continued). "ANGPTL3, ANGPTL4, ANGPTL5, ANGPTL7, and ANGPTL8 were significantly hypermethylated in tumor tissues." (PMID 35692877, 2022). "The elevated expression of angiopoietin-like 4 (ANGPTL4) is a common feature of many human tumor types, and its suppression impairs tumor growth through the enhancement of anoikis or apoptosis." (PMID 35328637, 2022). "Tumor growth is promoted by activating proliferation (BHLHE41, VWF, ANGPTL4, and possibly IGFBP3), and preventing the apoptosis of cancer cells (ANGPTL4)." (PMID 34046336, 2021). "In summary, our current study demonstrated that CRNDE and ANGPTL4 are upregulated, while miR-29b-3p is downregulated in CRC tumor tissues." (PMID 34680556, 2021). "This implies that macrophages play a pro-tumour role by upregulating endothelial genes, which were later identified as ECSCR, ANGPTL4 and ITGB447." (PMID 34732817, 2021). "The ANGPTL4 overexpression in CAAs is directed by IL-1β from neighboring TAMs with activated NLRC4 inflammasome and can be exacerbated by tumor hypoxia, resulting in cANGPTL4 aggregation in the TME." (PMID 33946986, 2021). "Moreover, among the known functions of ANGPTL4, the task of adapting to the hypoxic conditions of stage I/II ccRCC tumor development may correspond to the prevention of cancer cell apoptosis and a shift in redox regulation towards ROS formation, which stimulates tumor progression." (PMID 34046336, 2021). "Since ANGPTL4 exerts wide-ranging effects on diverse processes including glucose and lipid metabolism, inflammation, and angiogenesis, it is possible that hypoxia-induced synthesis and dispersal of this protein could significantly alter the course of tumour development." (PMID 33050615, 2020). "Based on the RNA-seq data, we observed that genes that suppress tumor angiogenesis, including SERPINE1, THBS1, SERPINB5, CD82 and ANGPTL4, were upregulated." (PMID 32106543, 2020). "The location of tumor lesion also affected the expression level of ANGPTL1 (P = .0030), ANGPTL2 (P = .0014), ANGPTL3 (P = .0100), and ANGPTL4 (P = .0350) according to K‐W test." (PMID 32410376, 2020). "Samples of plasma, tumor, mesenteric (MES) and subcutaneous adipose tissue were removed for the determination of ANGPTL-4 levels and other proinflammatory factors." (PMID 31741709, 2019). "Herein, we found that 5 genes (Shisa3, PADI1, LRP2, ANGPTL4 and ALOX15B) were upregulated and 4 genes (CXCL9, ADAMDEC1, SCGB1A1/CC10, HLA-G) were downregulated in PR tumor tissues compared to SD tumor tissues." (PMID 31801598, 2019). "In fact, our results show a significant positive correlation between ANGPTL-4 tumor levels and those of IL-1 β, TNF-α, and NFκB, and a tendency toward a positive correlation of MCP-1 tumor levels (p < 0.06) in cancer cachexia patients." (PMID 31741709, 2019). "In this study, we identified that astrocytes secrete TGF-β2 to upregulate ANGPTL4 expression in TNBC cells, which contributed to tumor cell brain lesions." (PMID 31602400, 2019). "Many upregulated genes in the heat map have been reported to promote tumor metastasis, such as FOSB, OLR1, S100A9, MMP9, and ANGPTL4 36-40." (PMID 31598162, 2019). "In triple negative breast cancer (TNBC) ANGPTL4 and VEGFA together to heparin-binding epidermal growth factor (HB-EGF) play a pivotal role in the acquisition of tumor aggressiveness regulating tumor angiogenesis." (PMID 29389861, 2018). "Therefore, the expression and mechanism of ANGPTL4 may be related to tumor type." (PMID 30049845, 2018). "In 87% of cases, the proteins belonged to pathways related to local tumor progression, metastasis and/or angiogenesis (i.e. cathepsin D, MMP-9, eNOS, Leptin, ANGPTL4, autotaxin)." (PMID 29245929, 2017). "In conclusion, ANGPTL4 is uniquely induced by hypoxia in cultured SGC cells and is essential for tumour growth and resistance to anoikis through different mechanisms." (PMID 28894280, 2017).
tumor (continued). "In GBM LN229-vIII tumour xenografts, EGFRvIII induces ANGPTL4 expression through the ERK/c-Myc pathway and promotes tumour angiogenesis." (PMID 26362268, 2015). "Comparing the expression levels of ANGPTL4 mRNA between paired primary and recurred tumor tissues in 5 HCC patients, 4 recurred tumors (80%) were found to have significantly lower levels of ANGPTL4 mRNA than their matched primary tumors." (PMID 25148701, 2014). "In this study, we show the involvement of EGFRvIII in tumor angiogenesis in LN229, a GBM cell line, and that the induction of angiopoietin-like 4 (Angptl4) expression by c-Myc is involved in EGFRvIII-induced angiogenesis." (PMID 23617883, 2013). "In this study we examined the contribution of important HIF-responsive genes such as VEGF, CCND1, ANGPTL4, EGLN3, ENO2, GLUT1 and IGFBP3 to tumor growth in a xenograft model using immune-compromised nude mice." (PMID 24260413, 2013). "Constitutive knockdown of Angptl4 in LN229-vIII using shRNA significantly decreased the microvessel density in the tumor xenografts and suppressed tumor growth." (PMID 23617883, 2013). "Additionally, a previous study in breast cancer revealed that the induction of ANGPTL4 by TGFβ via Smad disrupts vascular endothelial cell-cell junctions, increases the permeability of lung capillaries and facilitates the trans-endothelial passage of tumor cells." (PMID 23251252, 2013). "Previous studies have also revealed that the induction of angiopoietin-like 4 (ANGPTL4) by TGFβ, via the Smad signaling pathway, is critical for the trans-endothelial passage of tumor cells resulting in tumor metastasis." (PMID 23251252, 2013). "Therefore, it is tempting to speculate that targeting these matricellular proteins (e.g., SPARC, ANGPTL4, and hdOPN) would either increase the infiltration of immune cells to inhibit tumor growth or induce apoptosis by stripping off their anoikis survival capabilities." (PMID 22481923, 2012). "Angiopoietin-like 4 (ANGPTL4), a crucial modulator of angiogenesis, is secreted by hypoxic tumor cells and can be absorbed by normoxic adjacent cells, thereby inducing radiation resistance in these bystander cells by inhibiting ferroptosis and diminishing lipid peroxidation." (PMID 40724808, 2025). "Angiopoietin-like 4, essential for new vessel formation and tumor survival under stress, was cut by 75.9% with KAE and 93.1% with cisplatin, effectively disrupting angiogenic signaling and tumor expansion." (PMID 41515404, 2025). "We hypothesize that the high EFFscore subgroup may secrete ANGPTL4 and MDK to activate myCAF populations, particularly LRRC15+ Fib and STRA6+ Fib, thereby driving late-stage ECM remodeling and promoting tumor invasion and metastasis." (PMID 41383622, 2025). "Our findings reveal that Angiopoietin-like 4 (ANGPTL4) exhibits significantly higher expression levels in adipocyte-rich tumor circumstance compared to the symbiotic environment lacking of adipocyte." (PMID 40616161, 2025). "Interestingly, ANGPTL-4 also plays a role in regulating the function of AKT/PKB, which is an upstream effector of glucose consumption and glycolysis during tumor metabolic reprogramming." (PMID 39856383, 2025). "This suppressive phenotype, however, is not present in all ccRCC cell lines, as knockout of ANGPTL4 or inhibition by treatment with anti-cANGPTL4 inhibits tumor growth in the 786O tumor model, a model with mutant VHL." (PMID 39105498, 2024). "By reducing tumor-favorable microenvironment factors such as CD68+ macrophage infiltration and changes to the profile of cytokines released by macrophages in the TME, Ad-ANGPTL4 treatment considerably reduced the development of HCC.." (PMID 38997297, 2024).